AQP7 (aquaporin 7)
Diseases named in the same sentence as AQP7 in open-access papers (continued):
Sharing a sentence is not in itself a finding about the gene and the disease.
Obesity (continued). "Further characterization of this AQP7 KO mouse line showed that after 12 weeks of age, AQP7 KO mice developed adult-onset obesity with adipocyte hypertrophy and whole-body insulin resistance." (PMID 29300344, 2018). "As human AQP7 gene is localized in a chromosomal region with reported linkage to type 2 diabetes (T2D) and the metabolic syndrome, AQP7 expression has been particularly studied in patients suffering from obesity, T2D and metabolic syndrome." (PMID 30042691, 2018). "In this regard, transgenic AQP7-knockout mice develop adult-onset obesity, hyperinsulinemia, increased intracellular triacylglycerol content and reduced β-cell mass in Langerhans islets." (PMID 29675407, 2018). "Obesity is associated with increased AQP3 and AQP9 expression and decreased AQP7 expression in human subcutaneous adipose tissue." (PMID 27763558, 2016). "Connection between obesity and secondary development of T2D and a common SNP (A953G) in the AQP7 promoter was reported in Caucasian individuals." (PMID 26594198, 2015). "Studies conducted in AQP7 null mice have related the depletion of AQP7 to the development of obesity and adipocyte hypertrophy." (PMID 24376702, 2013). "Several studies have been attempting to disclose the possible connection between AQP7 and obesity/diabetes." (PMID 24376702, 2013). "There is evidence pointing towards the role of AQP7 in glycerol release/uptake in adipocytes and a correlation between AQP7 deregulation and the development of obesity has been postulated." (PMID 24376702, 2013). "The plasma membrane aquaporin-7 (AQP7) has been shown to be expressed in adipose tissue and its role in glycerol release/uptake in adipocytes has been postulated and correlated with obesity onset." (PMID 24376702, 2013). "As a complement to the AQP7 expression studies within the obesity and diabetes backgrounds, it would be relevant to further investigate the mechanisms regulating AQP7 activity." (PMID 24376702, 2013). "BAT expresses AQP7, which decreases during cold exposure and increases with diet-induced obesity." (PMID 40927981, 2026). "Targeting AQP7 may offer novel therapeutic possibilities to combat obesity-related complications, particularly in chronic high-glucose exposure settings such as PD." (PMID 41203811, 2025). "Specifically, estrogen response elements in the promoter region of the AQP7 gene, which lead to fat catabolism in adipocytes, may provide an explanation for the onset of obesity during menopause." (PMID 40725460, 2025). "Hence, the precise regulatory mechanism linking obesity and AQP7 gene promoter methylation remains to be further elucidated." (PMID 39456161, 2024). "In addition to the extensive research on AQP7 in the adipose tissues of obese humans and rodents, AQP7 expression in skeletal muscle has gradually gained attention in studies on obesity." (PMID 39456161, 2024). "AQP3 activators may exert therapeutic effects on defects in the hydration, lubrication, and proliferation of the skin, bladder, vagina, and respiratory system, whereas AQP7 activators may be applicable as useful adjuvants for obesity treatment." (PMID 39195451, 2024). "In addition, sleeve gastrectomy, a surgical procedure, has shown positive effects on AQP7 in obesity treatment." (PMID 39456161, 2024). "Its effects have also been hypothesized to be strongly correlated with increased AQP7 expression, further evidencing the central role of AQP7 in anti-obesity research." (PMID 39456161, 2024). "The level of AQP7 expression in brown adipose tissue is also altered in obesity." (PMID 39456161, 2024). "There also appears to be a strong relationship between gender and AQP7 expression in obesity." (PMID 39456161, 2024). "In this study, we did not investigate the cellular or subcellular localization of AQP7 in the investigated adipose tissues, and further studies are needed to determine the relationship between the cellular and subcellular expression of AQP7 in adipose tissue and obesity." (PMID 39201693, 2024).
Obesity (continued). "Unfortunately, AQP7-KO mice exhibited obesity and insulin resistance after 12 weeks." (PMID 37691043, 2024). "Similar to the phenomenon noted in the white adipose tissue of AQP7 KO mice, the amounts of AQP7 mRNA and protein were diminishing in the abdominal subcutaneous white adipose tissues of individuals with different levels of obesity." (PMID 39456161, 2024). "In the multiple lineal regression analysis, whole-body adiposity contributed independently to 27% (p < 0.001) of AQP7 protein levels in BAT after controlling for body weight, suggesting the strong impact of obesity in the expression of AQP7 in this thermogenic fat depot." (PMID 36834823, 2023). "We hypothesized that AQP7 participates in the improvement of BAT whitening of rats with diet-induced obesity (DIO) 1 week after cold exposure and/or 1 month after bariatric surgery." (PMID 36834823, 2023). "The upregulation of AQP7 in diet-induced obesity might contribute to glycerol influx used for TG synthesis, and hence, brown adipocyte hypertrophy." (PMID 36834823, 2023). "AQP7 allows the bidirectional movement of water and glycerol across plasma membranes, with glycerol permeation being a central element of fat accumulation and the pathophysiology of obesity." (PMID 36834823, 2023). "Aqp7 knockout mice displayed adult-onset obesity and hyperglycemia." (PMID 37681902, 2023). "Another potentially interesting metabolic modulator in obesity is aquaporin-7 (AQP7)." (PMID 36038791, 2022). "(2020) found that Rb1 could markedly diminish the body weights of mice with HFD-induced obesity and the mechanism involved was that Rb1 enhanced AQP7 expression both in vivo and in vitro." (PMID 35639355, 2022). "The modulation of adipocyte AQP7 expression has been proposed as a target in obesity therapy." (PMID 32821266, 2020). "The altered expression of AQP7 is involved in the onset of obesity and metabolic disorders." (PMID 31963489, 2020). "In the present study, we aim to investigate whether HFD-induced obesity in mice results in a coordinated upregulation of AQP7 and AQP9 protein in WAT and the liver and whether the effect of HFD on glycerol metabolism is sex-specific." (PMID 33193093, 2020). "AQP7 is also known to play a pivotal role in glycerol metabolism in a wide range of tissues with implications for whole-body energy balance as well as the pathophysiology of obesity and development of insulin resistance." (PMID 32309443, 2020). "Regulation of AQP7 in adipose tissue appears crucial for obesity treatment." (PMID 32821266, 2020). "The upregulation of AQP7 expression or its functional activation might be an ideal approach for the treatment of obesity." (PMID 32821266, 2020). "Identified missense (R12C, V59L and G264V) and silent (A103A and G250G) AQP7 gene mutations in a cohort of Japanese subjects were not linked to obesity or diabetes." (PMID 31614661, 2019). "The phenotype of Aqp7 knockout mice is characterized by adult-onset obesity and hyperglycemia." (PMID 31614661, 2019). "In some cases, compounds that modify the transcription and translation of AQPs may also be beneficial such as modifying AQP7 expression as a treatment for obesity." (PMID 30934923, 2019). "In addition, AQP7 KO mice, fed on a high fat/high sucrose diet, demonstrated early onset of obesity and insulin resistance even at a young age." (PMID 29914059, 2018). "Recently, the pancreatic expression of AQP7 was reported to be increased in HFD fed obese rats, and when evaluating the effect of sleeve gastrectomy as a surgical intervention for the amelioration of obesity, a further increase in pancreatic AQP7 expression was observed." (PMID 29300344, 2018). "For obesity and metabolic pathologies AQP7 modulation therapy may be a viable solution to combat this ever-growing epidemic." (PMID 30555637, 2018).
Obesity (continued). "In a study conducted in 160 adult Japanese subjects, those individuals carrying homozygous missense mutations (R12C, V59L, and G264V) and silent mutations (A103A and G250G) in the AQP7 gene neither exhibit obesity nor diabetes." (PMID 29675407, 2018). "In conclusion, AQP7 is a significant modulator of glycerol metabolism in a wide range of tissues with implications for whole-body energy balance as well as the pathophysiology of obesity and development of insulin resistance." (PMID 29300344, 2018). "Interestingly, in human subcutaneous adipose tissue, obesity is associated with increased AQP3 and AQP9 expression and decreased AQP7 expression." (PMID 29186031, 2017). "In addition, obesity has been associated with increased AQP3 and AQP9 expression and decreased AQP7 expression in human subcutaneous adipose tissue." (PMID 29186031, 2017). "In contrast, overexpression of AQP7 improved insulin resistance in dexamethasone and TNFα-treated adipocytes and polyphenol-induced increase in AQP7 expression led to the inhibition of adipocyte hypertrophy in diet-induced obesity in rats." (PMID 27763558, 2016). "Studies conducted in Aqp7 null mice have linked the absence of AQP7 expression to the development of obesity and adipocyte hypertrophy." (PMID 27763558, 2016). "In conclusion, the present study demonstrates on one hand the expression of AQP7 in human adipocyte plasma membrane and on the other hand the presence of an alternative glycerol channel, AQP10, that working with AQP3 and AQP7 ensures glycerol exit from adipocyte, thus protecting humans from obesity." (PMID 23382902, 2013). "Differently from mice, AQP7 involvement in human obesity is far from been clearly defined." (PMID 23382902, 2013). "The causes for this sex-based difference in obesity-associated glycerol levels are not clear; however, it could relate to differences in the expression of adipose tissue AQP7 and hepatic AQP9, as shown in several mouse models of obesity." (PMID 40927981, 2026). "Thus, it was observed that in female, HFD-induced obese mice, adipose AQP7 expression is more elevated than in males, and this probably renders female mice less prone to obesity by facilitating the transport of glycerol out of WAT and other tissues to the blood." (PMID 40927981, 2026). "In addition, there is a definite relationship between AQP7 gene promoter methylation and obesity." (PMID 39456161, 2024). "In addition, the AP supplementation not only promoted AQP7 expression, but also reversed the hypomethylation status of the three CpG sites in the promoter of the AQP7 gene induced by the high-fat and high-sucrose diet, further emphasizing the significance of AQP7 in resisting diet-induced obesity." (PMID 39456161, 2024). "However, the impact of obesity on AQP7 expression in BAT and its metabolic consequences remain unknown." (PMID 36834823, 2023). "Thus, changes in BAT expression of AQP7 after bariatric surgery might reflect the improved brown adipocyte function by reversing WAT-like phenotype found in obesity." (PMID 36834823, 2023). "However, although AQP7-null mice in some other studies did not confirm obesity development, all these studies confirmed the association of AQP7 with glycerol metabolism." (PMID 33796134, 2021). "Another genetic variant in AQP7 gene, named G264V (rs62542743), although was reported to be related to an impaired exercise-induced plasma glycerol increase, neither associated with obesity nor associated with diabetes was identified." (PMID 30598999, 2018). "AQP7 gene missense and silent mutations were not correlated with obesity and T2D." (PMID 30042691, 2018). "Moreover, several expression studies in human adipose tissue, although not always in complete agreement, point to the upregulated AQP7 expression in visceral fat depots and downregulated AQP7 expression in subcutaneous fat mass in human obesity and type 2 diabetes disorders." (PMID 24376702, 2013).
Obesity (continued). "Carboxymethyl chitin demonstrated anti-obesity effects in 3T3-L1 adipocytes via AMPK and aquaporin-7 signaling pathways." (PMID 40004938, 2025). "This includes our previous study of the protein expression of AQP7 in abdominal SAT in healthy lean men and men with obesity and type 2 diabetes." (PMID 39201693, 2024). "By contrast, a negative correlation between the adipose tissue expression of AQP7 and PEPCK-C was found in women with upper-body obesity (r = −0.518, p = 0.011)." (PMID 39201693, 2024). "In order to evaluate the effect of diet-induced obesity (DIO) on WAT glycerol metabolism, we used immunoblotting to quantify the relative abundance of the glycerol channel AQP7." (PMID 33193093, 2020). "The coordination and regulation of AQP7 and AQP9 play an important role in the control of obesity and hepatic steatosis." (PMID 31275413, 2019). "Leptin administration in obese (ob/ob) mice strongly downregulated AQP3 and AQP7 in AT, while upregulating hepatic AQP9, perhaps to coordinately prevent lipid accumulation in AT and the liver during obesity." (PMID 29914059, 2018). "However, in the context of obesity, the accumulation of lipid storage and the consequent cell swelling could generate an internal hydrostatic pressure inducing membrane surface tension that could account for AQP7 down-regulation." (PMID 24376702, 2013). "It was also found that the AQP7 gene promoter contains CpG island diet-induced-obesity models in rats, but no change in AQP7 gene promoter methylation due to a high-fat, high-sucrose diet." (PMID 39456161, 2024). "As with our results, no significant changes in the expression of AQP7 mRNA have been reported in abdominal SAT in individuals with obesity with a mean BMI < 35 kg/m2." (PMID 39201693, 2024). "Third, across the different WAT depots, the expression of AQP7 protein positively correlated with the expression of ATGL and HSL, whereas a negative correlation with the protein expression of PEPCK-C was found in women with upper-body obesity." (PMID 39201693, 2024). "The lack of AQP7 is related to the increase of glycerol kinase activity and triglyceride accumulation in adipose tissue, resulting in secondary development of obesity and insulin resistance." (PMID 35245343, 2022). "This peptide was shown to decrease triglycerides accumulation in hypertrophic adipocytes in vitro through AQP7 mRNA and protein upregulation via PI3K signaling pathway, revealing that apelin-13 is a promising starting point to develop novel treatments against obesity and related health problems." (PMID 35187089, 2022). "In contrast to the effects observed in rodents, a lack of AQP7 in humans did not correlate with obesity or type two diabetes." (PMID 35163313, 2022). "Leptin deficiency was associated with obesity and NAFLD showing increased AQP3 and AQP7 expression levels in white adipose tissue with no changes in AQP9 expression." (PMID 35187089, 2022). "AQP7-null mice showed accumulation of cellular glycerol, triacylglycerols (TAG) and glycerol kinase up-regulation, which leads to development of progressive adipocyte hypertrophy and early obesity onset." (PMID 33796134, 2021). "However, further studies are needed to confirm that the coordinated upregulation of AQP7 and AQP9 in relation to obesity also occurs at the protein level." (PMID 33193093, 2020). "In male AQP7 knockout mice, increased activity of glycerol kinase (GlyK) in WAT has been reported alongside increased storage of triglyceride, which in turn led to obesity and secondary development of T2D." (PMID 33193093, 2020). "Depending on their genetic background, Aqp7 knockout mice were shown to either develop or not develop obesity." (PMID 30042691, 2018). "Selective modulation of AQP7 and AQP9 may constitute a promising approach for controlling obesity and metabolic-related disorders." (PMID 29977890, 2018).
Obesity (continued). "Our results show that leptin restores the coordinated regulation of fat-specific AQP7 and liver-specific AQP9, a step which might prevent lipid overaccumulation in WAT and liver in obesity." (PMID 26159457, 2015). "Leptin deficiency was associated with obesity and NAFLD exhibiting an AQP3 and AQP7 increase in WAT, without changes in hepatic AQP9." (PMID 26159457, 2015). "The results do not support that obesity is associated with marked changes in the protein expression of HSL and AQP7 in WAT or that there is a depot-specific effect of being obese on the expression of AQP7 in WAT when comparing women with upper-body obesity with lean women." (PMID 39201693, 2024). "It is speculated that AQP7 may experience decompensation in the later stage of T2DM, leading to a reduction in the excretion of glycerol from adipocytes, which further aggravates obesity and exacerbates diabetic conditions." (PMID 39456161, 2024). "Finally, additional investigations are required to assess whether AQP7 and/or AQP12 could become suitable therapeutic targets for the treatment of obesity and/or type 2 diabetes." (PMID 31614661, 2019). "AQP3 and AQP7 may facilitate glycerol efflux from adipose tissue while reducing the glycerol influx into hepatocytes via AQP9 to prevent the excessive lipid accumulation and the subsequent aggravation of hyperglycemia in human obesity." (PMID 31275413, 2019). "In this regard, Aqp7-deficient mice backcrossed into the C57BL/6N genetic background develop adult-onset obesity but not in the young state, whereas Aqp7-knockout mice generated in CD1 mice did not exhibit excess body weight but showed an increase in whole-body fat content." (PMID 26594198, 2015). "Consistent results for AQP3, AQP7, and AQP9 expression are lacking in humans with obesity, insulin resistance, and type two diabetes, and the physiological roles of AQPs 3 and 7 in the liver are uncertain." (PMID 35163313, 2022). "On the other hand, lipopolysaccharide, known to play an important role in obesity, decreased glycerol permeability and increased TAG content in 3T3-L1 adipocytes, without modification of AQP7 protein expression." (PMID 30042691, 2018).
Insulin resistance (17 papers, 2016 to 2025). Increased resistance towards insulin, that is, diminished effectiveness of insulin in reducing blood glucose levels. "AQP7 deficiency has also been shown to result in insulin resistance." (PMID 37691043, 2024). "In addition, Aqp7 deficiency was shown to be associated with insulin-resistance in mice." (PMID 27763558, 2016). "Impaired AQP7 expression in adipocytes contributes to dyslipidemia and lipotoxicity, while defective glycerol transport via AQP7 aggravates insulin resistance and ectopic lipid deposition, linking metabolic imbalance to DKD progression." (PMID 40641971, 2025). "Conversely, there was a drop in AQP7 mRNA levels in the obese adolescents, which was accompanied by an increase in insulin resistance." (PMID 39456161, 2024). "Upregulated levels of AQP7 were reported in a mouse model of obesity in the skeletal muscle, indicating its role in insulin resistance." (PMID 36675000, 2023). "Obese‐ and insulin‐resistant mice show increased aqp7 and aqp9 expression, in spite of hyperglycemia." (PMID 35075822, 2022). "AQP7 is downregulated in terms of insulin resistance according to the in vitro studies on mice adipocytes where insulin resistance was induced by dexamethasone or TNFα." (PMID 34069293, 2021). "The sexual dimorphism in fat distribution and the gender-specific AQP7 levels may contribute to the lower prevalence of insulin resistance and metabolic disorders found in premenopausal women compared to men." (PMID 34069293, 2021). "However, in endocrine myopathies such as insulin resistance, AQP7 and AQP9 levels are elevated." (PMID 36675000, 2023). "Qutanhuoxue decoction may improve insulin resistance by restoring the expression of aqp7 and aqp9." (PMID 31275413, 2019). "However, whether the upregulation of AQP7 in muscle promotes the pathophysiological development of obese T2DM or is merely a response to the reduced insulin-mediated lipid oxidation inhibition in insulin resistance remains to be further studied." (PMID 39456161, 2024).